LEP (leptin)
Diseases named in the same sentence as LEP in open-access papers (continued):
Sharing a sentence is not in itself a finding about the gene and the disease.
Obesity (continued). "Theoretically, increased leptin from obesity should cross the blood-brain barrier and suppress appetite at the neurochemical level but obese individuals are almost always leptin resistant much in the same manner that diabetics are insulin resistant." (PMID 36143948, 2022). "Calculation of Pearson correlation index between obesity (BMI/waist circumference) and serum leptin level." (PMID 35989732, 2022). "When obese mice were infected with H. polygyrus, the gene expression of leptin was markedly decreased, thereby reducing the production of fatty acids and fighting against obesity." (PMID 35281054, 2022). "Overnutrition activates hypothalamic PERK and promotes leptin resistance during obesity development in mice." (PMID 36188456, 2022). "We did not observe the dose dependence in blood lipid level, however, high-dose of PPE was seen to significantly lower the leptin level in serum, which was in favor of mitigation of obesity." (PMID 36079890, 2022). "The interplay of the hormone leptin with the hypothalamus-pituitary-adrenal axis plays an important role in regulating energy balance, thereby contributing to obesity." (PMID 35480480, 2022). "Attributed to development of obesity, plasma levels of leptin and ceramides increased, while that of triglycerides (TG) decreased." (PMID 35431918, 2022). "In contrast to leptin as a pro-inflammatory cytokine, adiponectin possesses anti-inflammatory properties, with its levels typically decreasing in the context of obesity." (PMID 36686472, 2022). "Given the powerful short-term effect of celastrol on leptin action, this new bioactive compound appears as an interesting candidate to modulate long-term leptin action by acting on metabolic programming with the aim of preventing obesity." (PMID 35684076, 2022). "Leptin, which tends to be elevated in the serum of patients with obesity, has been shown to suppress TREG proliferation, while leptin deficiency is associated with a higher frequency of TREG." (PMID 35860241, 2022). "High serum levels are related to obesity, insulin sensitivity, physical conditioning, and low levels of leptin." (PMID 35008925, 2022). "In fact, leptin concentration has been decreased after using simvastatin in asthmatic mice with obesity, which reflects the importance of this adipokine in this pulmonary disorder." (PMID 36613991, 2022). "The negative results found by others can be explained by the lower degree of obesity in the participant samples since leptin levels vary according to fat percentage and BED." (PMID 35758834, 2022). "Chronic low-grade inflammation, present in obesity and favored by it, causes decreased muscle anabolic function, which is mediated by variations in the production of factors such as TNF, IL-6, leptin and GH." (PMID 35326591, 2022). "An important animal model for the study of amylin’s role in obesity in general, and in the amylin-leptin interactions in particular, has been the selectively-bred DIO rat." (PMID 35456307, 2022). "Various human studies demonstrated altered leptin metabolism in the placenta of mothers with obesity." (PMID 36189369, 2022). "The increase in visceral adipose tissue leads to adipocyte hypertrophy, which is considered a key event in insulin resistance in obesity and MS, as it not only elevates proinflammatory cytokine levels but also leads to leptin resistance." (PMID 35488354, 2022). "Neutralizing antibody injection triggers an immune response to endogenous oversecreted leptin, and maintaining lower circulating leptin is highly beneficial to obesity control in diet-induced obese mice." (PMID 35774455, 2022). "In this study, there was a positive correlation association in LEP G2548A and LEPR Q223R variants in obese subjects, indicating that these polymorphisms can increase obesity risk." (PMID 36551995, 2022).
Obesity (continued). "Obesity is characterized by leptin resistance in humans; however, the mouse model relies on leptin deficiency and does not accurately recapitulate the clinical obese HFpEF phenotype." (PMID 36483560, 2022). "Clinical and animal studies have found that offspring with high leptin levels do not develop the same “leptin resistance” early in life as adults with obesity who have high leptin levels." (PMID 36601002, 2022). "In particular, the adipokines leptin and adiponectin appear to have a role in the onset of obesity-derived pulmonary diseases by affecting systemic inflammation, immune Treg activity, and the Th17 and Th2 responses." (PMID 35806353, 2022). "Many studies report that leptin participates in the pathophysiology of neurovascular disease, obesity, endocrine disease, metabolism-related disease, and cancer." (PMID 35628510, 2022). "Previous studies have shown that the leptin-mediated JAK2-STAT3 signaling pathway is related to obesity." (PMID 35529938, 2022). "Male rats that were supplemented with physiological doses of leptin during the suckling period were more resistant to overweight/obesity and related metabolic complications both under standard diet and when exposed to a HF diet." (PMID 34523036, 2022). "As a typical feature of obesity, leptin resistance was involved in the hepatic steatosis during the development of MAFLD." (PMID 35444532, 2022). "The role of obesity is pivotal due to the increasedproduction of hormones derived from adipose tissue,especially leptin." (PMID 36273315, 2022). "On the other hand, rare forms of obesity that are uniquely due to defects of genes encoding for, e.g., FTO, melanocortin 4 receptor or leptin, have also been identified." (PMID 35741001, 2022). "In this review, we will focus on leptin, due to its involvement in the regulation of food intake and energy expenditure, studying its involvement in dementia and its relationship with obesity." (PMID 35563589, 2022). "Obesity is a chronic state of inflammation related to adipokines imbalance (i.e., high blood levels of leptin and low levels of adiponectin), which is a critical factor for cardiovascular disease." (PMID 35967818, 2022). "Elevated leptin and cholesterol levels are characteristic of obesity, and therefore these results further demonstrate the extent of the obese phenotype observed in Abi3–/– mice." (PMID 36620768, 2022). "There is also evidence that this influential population of neurons develops leptin resistance prior to the rest of the hypothalamus during obesity." (PMID 36499772, 2022). "Recent studies show that compared to normal-weight children, children with obesity tend to have higher circulating leptin that decreases with decreasing BMI." (PMID 36499740, 2022). "Both of these hormones are predominantly secreted by adipocytes (with some gastric production in the case of leptin), and they are important regulators of metabolic homeostasis that become abnormal in the disease of obesity." (PMID 35662920, 2022). "Chronic treatment with corticosterone was found to be equivalent to those found in diet‐induced obese mice, connecting the importance of leptin and obesity to AT." (PMID 35510321, 2022). "This study’s main purpose was to reveal the association of adipokines (leptin, adiponectin), hs-CRP, and IL-6 with cardiovascular risk factors (lipid profile, diabetes control, obesity, physical activity) in children and adolescents with T1D." (PMID 36010052, 2022). "A study has revealed that elevated levels of serum leptin were positively correlated to standard markers of obesity and showed the strongest correlation with hip circumference." (PMID 35628271, 2022). "Leptin signalling plays an important role during pregnancy and obesity independently and with known effects on leukocyte function needs to be considered as a mediator of any interaction between obesity and pregnancy." (PMID 35348641, 2022).
Obesity (continued). "Leptin resistance defined by a failure response to high circulating leptin level, presenting a decreased capacity of leptin to suppress appetite or increase energy cost, leads to overweight, obesity and other metabolic disorders." (PMID 33849593, 2021). "HFD-fed mice developed obesity, insulin resistance, increased plasma leptin levels, adipose tissue inflammation, gut permeability, dysbiosis, and NASH-associated fibrosis." (PMID 34944770, 2021). "Others tried to use cord blood adipocytokines such as leptin and adiponectin as objective markers to predict future obesity, in contrast to adiposity measurements, which are subjective and prone to measurement errors." (PMID 33669328, 2021). "Leptin and adiponectin are the classic adipokines of adipose tissue and have a substantial relationship in the pathogenesis of obesity and metabolic complications." (PMID 33807959, 2021). "More recent reports have shown that oleuropein supplementation at high concentration (0.59%) significantly decreased the body weight, decreased leptin concentration, and modulated gene expression related to obesity in mice." (PMID 33816636, 2021). "HFD and sleep debt share similar neuroinflammatory mediating mechanisms, leading to insulin/leptin resistance and anxiety, crucial for weight gain and obesity." (PMID 34621773, 2021). "Clinical studies where leptin has been used to treat obesity have identified that leptin also exhibits beneficial cognitive properties, which parallel the cognitive-enhancing actions of leptin in rodents." (PMID 33440796, 2021). "In individuals with severe obesity, elevated blood leptin levels and leptin resistance are usually observed." (PMID 33918997, 2021). "Despite these positive reports on the effect of leptin on the liver, the efficacy of leptin in preventing liver steatosis seems limited by obesity." (PMID 33935782, 2021). "Wild-type mice have a more diverse microbiota than leptin knockout mice; This can help mice resist obesity." (PMID 34557167, 2021). "After leptin transmits obesity signals to the brain, it can maintain energy balance and regulate weight by regulating the activities of neurons in multiple areas of the hypothalamus." (PMID 34485124, 2021). "A number of studies have used viral transfection of leptin through i.c.v. administration in an attempt to increase leptin levels and decrease obesity." (PMID 34947993, 2021). "Leptin knockout can relieve leptin’s inhibition of NPY neurons and cause obesity and inhibit NPY neurons by chemogenetic tools which can improve food intake and blood glucose levels in diabetic mice." (PMID 34307371, 2021). "In obesity, the levels of monocyte chemotactic protein 1 (MCP-1) and leptin are significantly elevated, causing a series of events that mediate chronic inflammation of the adipose tissue." (PMID 34421909, 2021). "Ectopic expression of Agouti in multiple tissues in these mice results in a yellow coat color, chronic hyperphagia, obesity, increased linear growth, leptin and insulin resistance, and hyperglycemia." (PMID 34604220, 2021). "The reduction in leptin levels indicates a decrease in adipose tissue and the prevention of obesity." (PMID 33535476, 2021). "The female DIO Western diet models (C57BL/6J) had free access to a high fat and sucrose-fructose and demonstrated obesity, insulin and leptin resistance, dysglycemia in the 150 to 200 mg/dL." (PMID 34063911, 2021). "In accordance, TLR4 loss-of-function mutation or intracerebroventricular injection of a TLR4 neutralizing antibody reduces obesity and leptin resistance." (PMID 34201844, 2021). "The plant-based inhibitor of PERK, celastrol, increases leptin sensitivity, resulting in decreased food intake and body weight in a murine model of diet-induced obesity (DIO)." (PMID 34549728, 2021).
Obesity (continued). "Leptin, which is dysregulated in obesity, is a polypeptidehormone with 16 kDa weight, produced mainly by whiteadipose tissue and secreted by lipocytes: leptin can affectthe immune processes, hematopoiesis, angiogenesis andreproduction." (PMID 33687165, 2021). "Especially, it is worth noting that obesity-related leptin has been confirmed to interfere with the endocrine therapy outcomes in BC patients, such as tamoxifen." (PMID 34350120, 2021). "Differences in leptin levels between the groups and depending on the degree of obesity were reliably detected." (PMID 35126755, 2021). "To address what kind of obesity-associated factors reduced the anticancer efficacy of AdipoRon, we examined the effect of glucose, insulin, IGF-1 and leptin on the survival of AdipoRon-treated Panc02-Luc-ZsGreen cells in vitro." (PMID 33536560, 2021). "So leptin and its receptors play a central role in weight regulation, and any disruption of this signaling system can lead to obesity." (PMID 34659432, 2021). "In this chapter, we discuss the main pathways regulating preovulatory follicle formation, the particular involvement of leptin signaling, and the disruptive effects of obesity and impaired leptin signaling." (PMID 33924072, 2021). "Leptin was initially described as an anti-obesity hormone; however, current studies have proved that its function concentrates on energy sufficiency rather than on excess." (PMID 35056501, 2021). "The adipocyte-derived ‘satiety promoting’ hormone, leptin, has been identified as a key central regulator of body weight and fertility, such that its absence leads to obesity and infertility." (PMID 34502119, 2021). "Several studies have investigated the relationships between LEP G2548A/LEPR Q223R polymorphisms and obesity, diabetes, insulin resistance, dyslipidaemias and cancer." (PMID 34407095, 2021). "As elevated leptin levels are a key feature of obesity, the prothrombotic state produced by hyperleptinemia, increases the risk for developing thrombotic complications in COVID-19." (PMID 33920604, 2021). "Leptin and leptin receptors therefore play a central role in weight regulation, and any disruption of this signaling system can lead to obesity." (PMID 34659432, 2021). "Capsaicin treatment in mice fed on an HFD for 10 weeks lowered obesity, fasting glucose, insulin, leptin, and hepatic TGs while increasing adiponectin mRNA/protein in the adipose tissue." (PMID 34234682, 2021). "There is firm evidence that genes influencing energy homeostasis and thermogenesis, adipogenesis, leptin-insulin signaling transduction, and hormonal signaling peptides play a role in the development of obesity." (PMID 34131278, 2021). "It has been reported that the relationship between obesity and thyroid nodules is probably related to leptin secreted by adipose tissue." (PMID 34452638, 2021). "Leptin and adiponectin produced by adipocytes are the major adipokines relating to the pathogenesis of obesity." (PMID 35008644, 2021). "In the present study, before and after acupuncture treatment, we measured the serum levels of leptin, prostaglandin E, and hormones in SD rats with simple obesity to explore the possible mechanism of acupuncture during the process of treating obesity." (PMID 34646336, 2021). "In the present section, we describe the signaling pathways leading major events orchestrating oocyte maturation and early embryo development, particularly, highlighting potential links to leptin signaling and its disruption during obesity." (PMID 33924072, 2021). "Just as type 2 diabetes involves desensitization to the hormone insulin, obesity involves desensitization of the body to the hormone leptin (a marker of energy storage)." (PMID 34659962, 2021). "The serum leptin level in patients with obesity was higher than that in the normal weight group, and a decrease in body weight led to a decrease in leptin levels." (PMID 34283904, 2021).
Obesity (continued). "This leptin resistance inhibits the AMPK signalling pathway, causing failure of systemic metabolism homeostasis and aggravating obesity and inflammation." (PMID 33830560, 2021). "A bidirectional interaction exists between leptin and inflammation, in which proinflammatory cytokines elevate the synthesis and release of leptin, contributing to a chronic inflammatory state in obesity." (PMID 33671547, 2021). "This makes leptin an interesting potential obesity variable for assessing the obesity paradox in SAH patients." (PMID 33866464, 2021). "One study reported that ablation of Tyr985 phosphorylation by a replacement of Tyr985 with Phe promotes diet-induced leptin resistance and obesity." (PMID 33849593, 2021). "The state of hyperleptinemia observed in obesity was already reported by several authors, who also demonstrated the ability of certain macronutrients in the diet (lipids specifically) to induce leptin resistance." (PMID 34568404, 2021). "High expression of leptin and low levels of adiponectin in obese patients have become the prerequisites for the occurrence of obesity-related tumors." (PMID 34485124, 2021). "Six-week administration of HSG4112 to HFD-induced obese mice led to dose-dependent normalization of obesity-related parameters, including body weight, muscle and adipose tissue weight, adipocyte size, and serum leptin/insulin/glucose levels." (PMID 32943760, 2021). "The potential effects of leptin and estrogen resistance on MG remodeling during the lactation cycle in condition of obesity still need to be explored." (PMID 33751362, 2021). "The study is aimed at investigating the curative effect of acupuncture on simple obesity and its influence on serum levels of prostaglandin E and leptin in Sprague-Dawley (SD) rats." (PMID 34646336, 2021). "We also compared blood levels of adiponectin and leptin as obesity-related proteins between obese cases and normal controls." (PMID 34440082, 2021). "The consequential increased ER stress, severe hyperleptinemia, leptin resistance, and obesity seen in HFD mice highlight the role of such impaired UPR response in the development of HFpEF." (PMID 34490381, 2021). "However, identification of novel mediators and a better understanding of the different metabolic pathways associated with the leptin signaling could result in the development of new potential therapeutic strategies to tackle obesity and its related metabolic disorders." (PMID 34183063, 2021). "Obesity is characterized by elevated leptin levels or hyperleptinemia and resistance to the anorectic and bodyweight-reducing effects of leptin." (PMID 34055005, 2021). "As expected, in positive individuals, leptin, the pro-inflammatory adipokine secreted primarily by the adipocytes and marker of obesity, was found higher in obese versus lean individuals (3536±636 pg/ml versus 7852±634 pg/ml, p<0.0001)." (PMID 33760825, 2021). "A decrease in fat mass results in the lowering of plasma leptin levels, stimulating appetite and suppressing energy expenditure, while in obesity, increased fat mass results in increased leptin levels, suppressing appetite until body weight is decreased." (PMID 33671547, 2021). "Obesity is also a state of chronic low-grade inflammation where adipose tissue expresses increased levels of leptin and decreased levels of adiponectin, which have been shown to effect foetal lung development and airway reactivity." (PMID 34043705, 2021). "In these studies, circulating leptin abundance was greater in those presenting with either sarcopenia or obesity, and greater still in individuals presenting with sarcopenic obesity." (PMID 33528828, 2021). "One of the most important adipokines is the leptin hormone, which is impeded by leptin resistance in these conditions despite its elevated levels both in obesity and in NAFLD and NASH." (PMID 33793621, 2021).